MDGA1 (MAM domain containing glycosylphosphatidylinositol anchor 1)
Description:
Required for radial migration of cortical neurons in the superficial layer of the neocortex (By similarity). Plays a role in the formation or maintenance of inhibitory synapses. May function by inhibiting the activity of NLGN2.
Synonyms: GPIM; MAMDC3
Tractability: Antibody: UniProt places it where antibodies can reach, with high confidence; its Gene Ontology location is reachable by antibodies, with high confidence; UniProt predicts a signal peptide or a membrane-spanning region; the Human Protein Atlas places it where antibodies can reach. PROTAC: its protein half-life has been measured.
Gene: Protein-coding gene on chromosome 6 (37,630,679 to 37,699,306, reverse strand). Ensembl gene ENSG00000112139.
Subcellular location: Cell membrane
Subcellular location (Human Protein Atlas): Plasma membrane; Golgi apparatus
Pathways (Reactome):
Metabolism of proteins: Post-translational modification: synthesis of GPI-anchored proteins
Gene Ontology:
Biological process: regulation of presynapse assembly; regulation of synaptic membrane adhesion; brain development; nervous system development; neuron migration; spinal cord association neuron differentiation
Cellular component: extracellular region; GABA-ergic synapse; plasma membrane; axon; cell surface; dendrite; membrane
Genetic constraint (gnomAD): Loss-of-function variants: 53 observed, 86.84 expected, observed/expected ratio (o/e) 0.61, 90% interval 0.49 to 0.77. The upper end of that interval is the gene's LOEUF score, 0.77, which puts it in group 3 of 6, group 1 being the genes least tolerant of losing a copy. Missense variants: 1,054 observed, 1,202 expected, observed/expected ratio (o/e) 0.88, 90% interval 0.83 to 0.92. Synonymous variants: 521 observed, 504.93 expected, observed/expected ratio (o/e) 1.03, 90% interval 0.96 to 1.11.
Homologues: Orthologues: chimpanzee MDGA1 (100% identical), macaque MDGA1 (99% identical), dog MDGA1 (98% identical), pig MDGA1 (98% identical), guinea pig MDGA1 (97% identical), mouse Mdga1 (96% identical), rat Mdga1 (96% identical), rabbit MDGA1 (87% identical), tropical clawed frog mdga1 (69% identical), zebrafish mdga1 (52% identical). Paralogues in human: MDGA2 (53% identical), MALRD1 (17% identical), MAMDC4 (15% identical), MAMDC2 (12% identical).
Diseases named in the same sentence as MDGA1 in open-access papers:
MDGA1 is named in the same sentence as 30 diseases in open-access papers, as found by Europe PMC text mining. Sharing a sentence is not in itself a finding about the gene and the disease. The quoted sentences say what the papers report.
schizophrenia (6 papers, 2018 to 2026). A major psychotic disorder characterized by abnormalities in the perception or expression of reality. "Focusing on chromosome 6, another cell-type-independent mQTL mapped to MDGA1, a major susceptibility locus for schizophrenia." (PMID 29884221, 2018). "In addition, the test was successfully used to clarify the memory deficit in mice with genetic mutations in a molecule, MAM domain‐containing GPI anchor protein 1 (MDGA1), suggested to be a schizophrenia susceptibility gene." (PMID 33089673, 2020). "The MDGA1 has been reported to have SNPs related to susceptibility to the schizophrenia." (PMID 33089673, 2020). "In addition, the validity of the test was evaluated using a genetically engineered mouse, heterozygous deficient in Mdga1 (Mdga1+/‐), which is related to schizophrenia." (PMID 33089673, 2020). "MDGA1 reportedly suppresses GABAergic synaptic inhibition and may be associated with schizophrenia." (PMID 41862769, 2026).
cognitive deficits (3 papers, 2022 to 2024). "It has been reported that MDGA1 can contribute to cognitive deficits through altering inhibitory synapse development and transmission in the hippocampus." (PMID 39348415, 2024). "In a proteomic analysis, NCAN, BCAN, CTSS, MSR1, MDGA1, and CPA2 were reported as upregulated in individuals with PTSD and comorbid mild cognitive impairment." (PMID 35625844, 2022).
autism (2 papers, 2011 to 2025). Persistent deficits in social interaction and communication and interaction as well as a markedly restricted repertoire of activity and interest as well as repetitive patterns of behavior. "Although our study identified Mdga1 while literature more strongly links Mdga2 to autism, both genes belong to the same MDGA family, which are known critical regulators of synaptic development and cortical circuit formation." (PMID 41331623, 2025).
autism spectrum disorder (2 papers, 2021 to 2026). A spectrum of developmental disorders that includes autism, and Asperger syndrome. "Here, we describe two patients with autism spectrum disorder (ASD) carrying missense mutations in MDGA1: p.Val116Met/p.Ala688Val and p.Tyr635Cys/p.Glu756Gln." (PMID 41862769, 2026).
breast carcinoma (2 papers, 2018 to 2024). "In this example, the association between SNP rs6458012 and the expression of MDGA1 in breast tumors (P = 1.5 × 10− 29) could not be attributed to breast cancer cells (P = 0.26) given the loss of an effect as tumor purity increased." (PMID 30205839, 2018).
multiple sclerosis (2 papers, 2021 to 2025). A progressive autoimmune disorder affecting the central nervous system resulting in demyelination. "To additionally validate MDGA1 expression as a biomarker for other inflammatory diseases, we analyzed a large publicly available single-cell dataset of PBMCs from multiple sclerosis (MS) patients." (PMID 41327488, 2025).
restless legs syndrome (2 papers, 2017 to 2025). A condition that occurs while resting or lying in bed; it is characterized by an irresistible urgency to move the legs to obtain relief from a strange and uncomfortable sensation in the legs. "The genotype distributions for the three MDGA1 single-nucleotide variants (SNVs)—rs10947690, rs61151079, and rs79792089—were in Hardy–Weinberg equilibrium in both the idiopathic restless legs syndrome (iRLS) patient group and the control group." (PMID 40724952, 2025). "The MAM domain-containing glycosylphosphatidylinositol anchor 1 (MDGA1) gene, which encodes a protein involved in synaptic inhibition, has been identified as a potential risk gene for restless legs syndrome." (PMID 40724952, 2025). "The BI-ENRICH algorithm showed that most of the top pathways identified for restless legs syndrome were related to neurodevelopment, including neurogenesis (genes MDGA1, MYT1, NTNG1, and SEMA6D), cell-junction organisation (PKP4 and SMAD3), and axon guidance (NTNG1 and SEMA6D)." (PMID 29029846, 2017).
Anxiety (1 paper, 2024). Intense feelings of nervousness, tension, or panic often arise in response to interpersonal stresses. "The normalization of the cytoplasmic gephyrin aggregates correlates well with the partial normalization of sIPSC frequency and amplitude, as well as with the partial normalization of the anxiety behavior in the female Nlgn2/MDGA1 dKO mice." (PMID 39284869, 2024). "Accordingly, we were unable to determine whether the anxiety phenotype of Nlgn2 KO mice is also ameliorated in male Nlgn2/MDGA1 dKO mice." (PMID 39284869, 2024). "We show that combined deletion of Nlgn2 and MDGA1 results in a partial reversal of the prominent anxiety phenotype observed in female Nlgn2 KO mice, consistent with the normalization of gephyrin aggregates and the partial normalization of sIPSC frequency in CA1 pyramidal neurons." (PMID 39284869, 2024). "In the present study, we used an open field task to test whether this anxiety phenotype is modulated in Nlgn2/MDGA1 dKO or Nlgn2 KO/MDGA2 Het mice." (PMID 39284869, 2024). "boundary was observed in Nlgn2/MDGA1 dKO mice, accompanied by a partial normalization of defects in sIPSC characteristics in CA1 pyramidal neurons and of the anxiety-related behavior in an open field test." (PMID 39284869, 2024). "Surprisingly, however, male Nlgn2 KO mice in this experiment did not display the anxiety phenotype previously observed, likely due to complex interactions with strain background or parental behavior of the Nlgn2 Het/MDGA1 Het breeders." (PMID 39284869, 2024). "We show that loss of MDGA1 expression, but not heterozygous deletion of MDGA2, ameliorates the abnormal cytosolic gephyrin aggregation, the reduction in inhibitory synaptic transmission and the exacerbated anxiety-related behaviour characterizing Nlgn2 knockout (KO) mice." (PMID 39284869, 2024). "Taken together, our observations indicate functional interactions between MDGA1 and Nlgn2 KOs, but not between MDGA2 and Nlgn2 KOs, in modulating the neuronal circuits that regulate anxiety-related avoidance behaviors." (PMID 39284869, 2024).
asthma (1 paper, 2017). "The results showed that gene expressions of both MEF2C and MDGA1 were significantly downregulated in patients with either mild-moderate or severe asthma compared to normal controls." (PMID 29137293, 2017). "In conclusion, our study shows that aberrant regulations of mir-203a to MEF2C and mir-3065-3p to MDGA1, as well as downregulation of KCNJ2, play important roles in airway epithelial homeostasis in asthma." (PMID 29137293, 2017). "We proposed that aberrant regulations of mir-203a-MEF2C and mir-3065-3p-MDGA1, as well as downregulation of KCNJ2, play important roles in airway epithelial homeostasis in asthma." (PMID 29137293, 2017).
Chagas disease (1 paper, 2022). A parasitic infection caused by Trypanosoma cruzi. "All those genes are involved in biological process associated to Chagas disease: nervous system (LHX6, POU6F2, MDGA1, DISC1, PCSK9), immune system (ZMIZ, HLA-DRB1), Wnt pathway (DISC1), ion transport (KCNK15, PCSK9), striated muscles (SMYD3) or ATP metabolic process (ATP5S)." (PMID 36248819, 2022).
COVID-19 (1 paper, 2024). A disease caused by infection with severe acute respiratory syndrome coronavirus 2. "The StablL model also selected MDGA1, a previously unknown candidate biomarker of COVID-19 severity." (PMID 38168992, 2024).
depression (1 paper, 2025). "Given that the hyperactivity of LHb neurons contributes to the pathophysiology of depression 7, and Mdga1 deficiency attenuated the activity of LHb neurons, we next examined whether conditional knockout of Mdga1 in the LHb altered rodent behavioral analogs of anhedonia and behavioral despair." (PMID 39897557, 2025). "Use of an MDGA1 binding deficient Nlgn2 genetic variant further confirmed the central regulatory role this complex (MDGA1/Nlgn2) plays in providing the molecular substrates for stress-mediated depression resilience." (PMID 39897557, 2025). "To explore these questions, we combined genetic manipulations of MDGA1/Nlgn2 with functional assessment of LHb synapses in mice subjected to restraint stress and subsequent biobehavioral assays for depression." (PMID 39897557, 2025). "Taken together, these results indicates that the interaction between MDGA1 and Nlgn2 in the LHb may play roles in the regulation of LHb function in the development of stress-induced depression." (PMID 39897557, 2025). "Given the essential role of the LHb in regulation of depression, we next assessed whether the expression patterns of MDGA1 and Nlgn2 were changed using a mouse model of chronic stress, which is a major risk factor for depression onset." (PMID 39897557, 2025). "Therefore, genetic removal of MDGA1 prevents the LHb from signaling the onset of depression during stressful events, providing a novel therapeutic target for limiting the effects of stress on genesis of depressive states." (PMID 39897557, 2025). "Targeting MDGA1/Nlgn2 complexes residing at GABAergic synapses within the lateral habenula may be viable for alleviating core behavioral symptoms of major depression." (PMID 39897557, 2025). "We further probed if altering MDGA1-Nlgn2 interactions affects measures of depression-like behaviors in mouse models, and whether preventing this interaction reverses these effects." (PMID 39897557, 2025). "Notably, these effects are observed during ARS when the cellular events that prime depression onset take place, suggesting that MDGA1 modulates stress resistance at the earliest stages of stress-induced depression." (PMID 39897557, 2025). "Finally, manipulating the expression MDGA1 or binding of MDGA1 to Nlgn2 can serve as a molecular tool for selectively modulating inhibitory synaptic drive in the LHb to prevent the onset of major depression following stress." (PMID 39897557, 2025). "To probe whether the disruption of MDGA1 and Nlgn2 interactions in the LHb also alleviates chronic stress-mediated depression-related behaviors in mice, we generated transgenic mice with a conditional knock-in Nlgn2 mutation (Nlgn2mutflox/flox)." (PMID 39897557, 2025). "LHb neuronal responses to chemogenetic activation of the LH-LHb pathway or acute restraint stress were similarly muted in the Nlgn2mut/mut mice, confirming that decreased binding of MDGA1 to Nlgn2 is specifically required for conferring resistance to stress-induced depression." (PMID 39897557, 2025). "Elevated levels of MDGA1 within the LHb, further emphasizes the highly regional specificity of MDGA1 expression in the brain, which may add to the complexity of Nlgn2's regulation of mood related brain circuitry as well as provide specific drug target for depression." (PMID 39897557, 2025). "Importantly, Mdga1 knockout did not alter the propensity for onset of depression per se; However, depression resistance was consistently observed when mice underwent behavioral tests for exaggerated stress responses (TST, FST, SPT)." (PMID 39897557, 2025).
endometrial adenocarcinoma (1 paper, 2022). "After MDGA1 was removed, the remaining candidate hub genes (RECK, CFL2, TGFBR3, TPM2, and C10ORF91) affecting the survival rate of endometrial adenocarcinoma in the MEbrown module and MEturquoise module were selected." (PMID 35123404, 2022).
insomnia (1 paper, 2019). A sleep disorder characterized by difficulty in falling asleep and/or remaining asleep. "The association with insomnia risk at the MDGA1 locus is an example of this, particularly given that it has recently been validated by a large-scale GWAS32." (PMID 30820025, 2019). "As an example of this, there was evidence that insomnia risk and molecular traits share a CCV at the MDGA1 locus (combined PPA = 85.8%)." (PMID 30820025, 2019).
kidney cancer (1 paper, 2018). Primary or metastatic malignant neoplasm involving the kidney. "MDGA1 knockdown resulted in decreased migration and proliferation in ACHN, 786-O and Caki-2 kidney cancer cell lines." (PMID 29435133, 2018).
lung carcinoma (1 paper, 2024). "These genes include GRIA3, TAF7L, ARL14, PCDHGA9, MDGA1, ZFPM2, OSR2, TMC8/TMC6, HCN2, and CDK5R2, which are likely to be relevant in human lung cancer and are also epigenetically deregulated upon exposure to ECS in our animal study." (PMID 39273313, 2024).
memory impairment (1 paper, 2024). "Our study demonstrated that treatment with D-cycloserine attenuated LTP and memory impairment in Mdga1+/− mice but not in Mdga1−/− mice." (PMID 39273620, 2024).
Obesity (1 paper, 2023). Accumulation of substantial excess body fat. "This pilot study indicates that the plasma proteins alpha-2-MRAP, HAGH, Siglec-9, MDGA1, EDA2R, and IL12 are negatively associated with cognitive performance in a sample of older adults with overweight/obesity and MetS." (PMID 36964401, 2023). "Here, we showed a significant increase in NPX in 6 proteins (alpha-2-MRAP, HAGH, Siglec-9, MDGA1, EDA2R, and IL12) in the l-GCF group of older adults with overweight/obesity and MetS from the PREDIMED-Plus cohort." (PMID 36964401, 2023).
posttraumatic stress disorder (1 paper, 2023). "Our findings support results from a previous study that found that MDGA1 was upregulated in cognitively impaired subjects with and without posttraumatic stress disorder." (PMID 36964401, 2023).
renal carcinoma (1 paper, 2018). A carcinoma arising from the epithelium of the renal parenchyma or the renal pelvis. "We found that MDGA1 knockdown decreased renal cancer cell migration and proliferation similarly to restoration of levels of miR-1 and miR-663." (PMID 29435133, 2018).
cancer (4 papers, 2018 to 2024). A tumor composed of atypical neoplastic, often pleomorphic cells that invade other tissues. "miR-663a is predicted to target MDGA1 and is reported in literature to induce cell differentiation and suppress tumor growth, invasiveness and cellular migration in multiple cancer types." (PMID 29435133, 2018). "We furthermore discovered 5 genes (MDGA1, VEGFC, MCM10, CTBP1-DT, CHMP4A) with three OS correlations, and 22 genes with two OS correlations, across eight cancer types." (PMID 32764426, 2020). "MDGA1, FRAS1 or the targeting miRNAs can be potential adjuvant therapeutic targets, through inhibition of cancer cell migration, thus eliminating the development of resistance and metastasis." (PMID 29435133, 2018).
neurodevelopmental disorder (2 papers, 2024 to 2026). A behavioral and cognitive disorder with onset during the developmental period that involves impaired or aberrant development of intellectual, motor, or social functions. "Chronic genetic dysfunction is recognized as a cause of developmental disorders, and Mdga1+/− mice may serve as a model for investigating specific types of neurodevelopmental disorders." (PMID 39273620, 2024). "However, it has been unclear whether and how MDGA1 dysfunction causes neurodevelopmental disorders." (PMID 41862769, 2026). "Our findings verified the functional relevance of MDGA1 synaptic suppressors on proper brain function and provided evidence supporting the idea that certain types of neurodevelopmental disorders might be ameliorated by medication in adulthood." (PMID 39273620, 2024).
psychiatric disorder (2 papers, 2016 to 2024). A disorder characterized by behavioral and/or psychological abnormalities, often accompanied by physical symptoms. "Given that both Nlgn2 and the MDGA1 have been correlated with many psychiatric disorders, our data support the notion that cytosolic gephyrin aggregation may represent an interesting target for novel therapeutic strategies." (PMID 39284869, 2024). "A further detailed understanding of how Nlgn2 and MDGA1 differentially regulate gephyrin aggregation, and how these aggregates affect GABAergic synapse function, may therefore be relevant towards identifying pathophysiological mechanisms in Nlgn2- and MDGA1-related psychiatric disorders." (PMID 39284869, 2024).
bacterial infection (1 paper, 2025). "Nevertheless, although none of the patients included in this cohort experienced significant viral reactivation of CMV, EBV, HHV6, HSV or bacterial infection within the observation period, it is conceivable that responses to other pathogens may contribute to induce MDGA1 expression." (PMID 41327488, 2025).
MDGA1 also shares sentences with these, for which no sentence is quoted: tumor (3 papers); bipolar disorder (2); breast tumors (1); microcephaly (1); neurological diseases (1); Williams-Beuren syndrome (1).